PTPN22 (protein tyrosine phosphatase non-receptor type 22)
Diseases named in the same sentence as PTPN22 in open-access papers (continued):
Sharing a sentence is not in itself a finding about the gene and the disease.
autoimmune disease (continued). "The role of PTPN22 in some but not all autoimmune diseases suggests a common underlying pathway for this subset of diseases that may be related to STR length and/or mutability." (PMID 24988487, 2014). "Our previous results on the absence of the association with this PTPN22 polymorphism in other autoimmune diseases such as RA and Takayasu's arthritis in this population underlines the specificity of the current finding in AChR-MG, also supporting the relationship with specific humoral autoimmunity." (PMID 25119822, 2014). "In conclusion, the sharing of a similar genetic background suggests that different autoimmune diseases may have similar pathogenic mechanisms, and the shared association with CTLA-4 and PTPN22 variants affects the threshold for activation or deactivation of autoreactive T cells." (PMID 25452756, 2014). "For example, a misssense SNP (R620W, rs2476601) in protein tyrosine phosphatase non-receptor type 22 (PTPN22) has been shown to be associated with several autoimmune diseases including T1D, rheumatoid arthritis and Crohn's disease (CD) but with opposite directions of association." (PMID 25144376, 2014). "Given that specific therapies directed toward Lyp will be available in the near future for various autoimmune diseases, there could be clinical-therapeutic consequences as well, and, on these grounds, the approach based on PTPN22 might be different from North to South." (PMID 21949702, 2011). "Furthermore, there is precedent for this because the PTPN22 gene has been associated with a variety of autoimmune diseases, although, interestingly and unlike the IL2RA/CD25 gene, not with MS." (PMID 19116909, 2009). "In view of our results we can not support firmly any hypothesis, but it seems clear that at least IgAD is not a conventional autoimmune disease, as shown by the lack of association with PTPN22 1858T." (PMID 16539704, 2006). "Among the other genes (PTPN22, AP4B1, BCL2L15, and PHTF1) were those related to bovine leukemia virus and human autoimmune diseases." (PMID 32083286, 2020). "Additional immune-regulatory loci include MICA/MICB, CTLA4, PTPN22, CIITA, CLEC16A, CD274 (PD-L1), and NLRP1 (NALP1)—variants shared with other autoimmune diseases, underscoring common immune checkpoints rather than AAD-specific genes." (PMID 41465179, 2025). "The driver SNP with the most colocalizations between IIM and IMD is rs2476601, a missense variant of PTPN22 and one of the best-known non-MHC risk variants associated with autoimmune disease." (PMID 39044428, 2024). "These possibilities can be further examined in T cells from healthy subjects and from subjects with autoimmune disease, as well as in mouse models of autoimmune disorders, such as the NOD strain, in which both Ubash3a and Ptpn22 were shown to contribute to the development of T1D." (PMID 37240014, 2023). "Our study reveals a new role for PTPN22 without phosphatase activity in immune system homeostasis and provides new data that contribute to our understanding of autoimmune diseases." (PMID 37833951, 2023). "Among genetic factors, the protein tyrosine phosphatase non-receptor type 22 (PTPN22) is one of the most important genes associated with the development of SLE and other autoimmune diseases." (PMID 36428917, 2022). "The protein tyrosine phosphatase nonreceptor 22 (PTPN22) and signal transducer and activator of transcription factor 4 (STAT4) have been recognized as susceptibility genes for numerous autoimmune diseases." (PMID 25781893, 2015). "Many of the non-HLA genes, such as PTPN22 and CTLA-4, have been previously studied in MG and other autoimmune diseases and their association with MG has been reevaluated in more cohesive groups of patients." (PMID 24294607, 2013). "Thus, PTPN22 is considered the strongest non-HLA (non-Human Leukocyte Antigen) candidate for autoimmune disease development, including RA." (PMID 41195177, 2025).
autoimmune disease (continued). "Further investigation into the regulation of PTPN22 and these other phosphatases in T cell is warranted to understand the complex intricacies of how T cells are activated and how TCR signaling pathways can be exploited to develop targeted immunotherapies for autoimmune diseases." (PMID 40911684, 2025). "Epidemiological and cellular studies within the context of autoimmune diseases have illuminated the significance of protein tyrosine phosphatase nonreceptor type 22 (PTPN22) as a critical regulator of T cell receptor (TCR) signaling, pivotal in immune response modulation and cancer." (PMID 39451542, 2024). "Previous studies reported associations of PTPN22 and NLRP3 polymorphisms with several autoimmune diseases suggesting their general role in the etiology of autoimmunity, however these risk alleles are not shared among all autoimmune disease." (PMID 30915320, 2019). "In future studies, the role of PTPN22 in the process of autoimmune tolerance breaking during the initial phase of autoimmune disease as well as the negative immunoregulatory effect of the CTLA-4 gene should be determined to reveal the common mechanisms of these diseases." (PMID 28133421, 2017). "The PTPN22 gene, encoding the lymphoid tyrosine phosphatase LYP, has emerged as one of the major non-HLA risk factors for a wide range of autoimmune diseases, including type 1 diabetes, rheumatoid arthritis (RA), systemic lupus erythematosus, Graves’ disease and others." (PMID 24498279, 2014). "Ptpn22 is rarely reported in B cells but acts as a negative regulator of Src and Syk family kinases downstream of the T cell receptor (TCR), and mutations in Ptpn22 are associated with an increased susceptibility to autoimmune diseases including rheumatoid arthritis and systemic lupus erythematosus." (PMID 34594327, 2021). "As an autoimmune disease whose pathogenesis is not completely clear, studying the correlation between ITP pathogenesis and PTPN22 gene SNP1858 and SNP1123, and then understanding the pathogenesis of ITP at the gene level can provide new ideas enlightening research about ITP mechanism and treatment." (PMID 35692826, 2022).
rheumatoid arthritis (142 papers, 2005 to 2026). A chronic, systemic autoimmune disorder characterized by inflammation in the synovial membranes and articular surfaces. "Numerous studies in Egypt highlight a correlation between the PTPN22 rs2476601 polymorphism and rheumatoid arthritis (RA) susceptibility." (PMID 40983977, 2025). "Polymorphisms in PTPN22 are associated with the incidence of rheumatoid arthritis, leading to immune dysregulation through the stimulation of the immune system’s main components and osteoclasts." (PMID 40305360, 2025). "SNP 1858C>T of PTPN22 has been linked to several multisystem autoimmune disorders including systemic lupus erythematosus, rheumatoid arthritis, type 1 diabetes, Graves disease and Hashimoto thyroiditis." (PMID 40635160, 2025). "Rheumatoid arthritis (RA) susceptibility is influenced by genetic polymorphisms such as PTPN22 and PADI4, though their associations vary significantly across ethnic populations." (PMID 40983977, 2025). "PTPN22 is strongly associated with type 1 diabetes, systemic lupus erythematosus, and rheumatoid arthritis." (PMID 38947339, 2024). "Research on PTPN22 has predominantly been centred on its association with rheumatoid arthritis, type 1 diabetes mellitus and autoimmune thyroid diseases." (PMID 39238070, 2024). "The associated phenotypes of PTPN22 mainly include thyroid diseases, rheumatoid arthritis and diabetes, which are relevant to immune abnormalities." (PMID 35639771, 2022). "The present study aimed to confirm the role of the PTPN2: rs478582-C and PTPN22: rs2476601-A SNPs in the inflammatory pathogenesis associated with Crohn’s Disease and Rheumatoid Arthritis." (PMID 34445589, 2021). "The R620W variant in protein tyrosine phosphatase non-receptor type 22 (PTPN22) is associated with rheumatoid arthritis, lupus and type one diabetes and is a mutation present in the human population." (PMID 33767692, 2021). "Reduction of Lck, Lat, Zap70 and Prdm1 expression in T cells and a SNP mutation in Ptpn22 have been associated with rheumatoid arthritis, systemic lupus erythematosus and T1D in humans." (PMID 31235823, 2019). "These SNPs were tested in a case–control analysis (n =908 cases/1,260 controls from the North American Rheumatoid Arthritis Consortium I (NARAC-I)) for significant heterogeneity of PTPN22 association in function of the SNP genotypes." (PMID 25260880, 2014). "Other examples included PTPN22 (AUC = 0.63), associated with two diseases in our benchmark displaying diverse phenotypes (rheumatoid arthritis, OMIM #180300, and systemic lupus erythematosus, OMIM #152700)." (PMID 23921638, 2013). "PTPN22 also has well-established associations with multiple autoimmune conditions, including type 1 diabetes, rheumatoid arthritis, systemic lupus erythematosus, juvenile idiopathic arthritis, Graves' disease, systemic sclerosis, and alopecia areata." (PMID 22493691, 2012). "PTPN22 has been shown to be associated with susceptibility to a number of immune related-diseases, such as type 1 diabetes (T1D), rheumatoid arthritis (RA) and systemic lupus erythematosus (SLE)." (PMID 22396730, 2012). "The number of copies of the HLA-DRB1 shared epitope, and the minor alleles of the STAT4 rs7574865 and the PTPN22 rs2476601 polymorphisms have all been linked with an increased risk of developing rheumatoid arthritis." (PMID 22937072, 2012). "To date, no data are available regarding the possible association between PTPN22 1858C>T polymorphism and rheumatoid arthritis in patients of Italic ancestry." (PMID 21949702, 2011). "Genetic variants in TRAF1C5 and PTPN22 genes have been shown to be significantly associated with arthritis rheumatoid in Caucasian populations." (PMID 21492465, 2011). "To define, by means of a systematic review and meta-analysis, the association between the PTPN22 1858C>T polymorphism distribution in Europe and rheumatoid arthritis." (PMID 21949702, 2011).
rheumatoid arthritis (continued). "Analysis of association of PTPN22 ‘haplotype 6–10’ group (rs12144309: C>T) with rheumatoid arthritis." (PMID 20975833, 2010). "There are also some studies covering regions including genes PTPN22 and TRAF-C5, and at least two alleles of PTPN22 were associated with increased risk for rheumatoid arthritis." (PMID 20018001, 2009). "In this paper, we conduct genome-wide searches for RA-associated gene-gene interactions that involve PTPN22 or HLA-DRB1 using the Genetic Analysis Workshop 16 Problem 1 data from the North American Rheumatoid Arthritis Consortium." (PMID 20017999, 2009). "At least two alleles of PTPN22 have been implicated as causing increased risk for rheumatoid arthritis; the R620W allele in rs2476601 (hCV16021387) confers 1.7- to 1.9-fold increased risk to heterozygotes and higher risks to homozygous carriers." (PMID 20018009, 2009). "Gender-dependent association of PTPN22 has been described with rheumatoid arthritis and with psoriatic arthritis, showing a predominant effect in male in both cases." (PMID 17697317, 2007). "We applied our method to two data sets provided by the North American Rheumatoid Arthritis Consortium (NARAC): the PTPN22 candidate gene data and the association mapping data." (PMID 18466518, 2007). "A variant of PTPN22 (encoding a lymphoid-specific protein tyrosine phosphatase) is modestly associated with multiple autoimmune diseases (rheumatoid arthritis, SLE, type 1 diabetes, and Graves' disease)." (PMID 17940599, 2007). "Moreover, a missense polymorphism in PTPN22, which leads to a R620W substitution in the C terminus of PTPN22, is a common risk factor for multiple autoimmune diseases including type I diabetes mellitus, systemic lupus erythematosus, and rheumatoid arthritis." (PMID 39173071, 2024). "Additionally, it is noteworthy that human PTPN22 mutations associated with alopecia areata and rheumatoid arthritis, also negatively regulates lymphocyte activation by reducing the PTPN22 phosphatase activity." (PMID 34966743, 2021). "Analysis of association of PTPN22 ‘haplotype 4’ (rs3811021: A>G) with rheumatoid arthritis." (PMID 20975833, 2010). "Analysis of association of PTPN22 ‘haplotype 5’ (rs3789607: T>C) with rheumatoid arthritis." (PMID 20975833, 2010). "Alleles at the PTPN22 locus have been shown to confer an increased risk for rheumatoid arthritis." (PMID 20018009, 2009). "In conclusion, PTPN22 R620W SNP is a risk factor for rheumatoid arthritis." (PMID 18466483, 2007). "The second study, also performed in a white North American population, compared the frequency of the PTPN22 risk allele between the Study of New Onset Rheumatoid Arthritis cohort and the control sample of the previous study, observing the association between the 1858T allele and early RF+ RA." (PMID 16277672, 2005). "It is well established that PTPN22 single nucleotide polymorphisms (SNPs) are associated with several autoimmune diseases, including rheumatoid arthritis (RA), type 1 diabetes mellitus (T1DM), and systemic lupus erythematosus (SLE)." (PMID 41294867, 2025). "This enzyme has gained enormous interest due to a genetic SNP of its gene PTPN22 rs2476601 (R620W), which has been associated with several human autoimmune diseases, including rheumatoid arthritis (RA)." (PMID 40725063, 2025). "The non-synonymous PTPN22 polymorphism C1858T (encoding R620W) is a strong risk factor for the development of multiple autoimmune diseases, including rheumatoid arthritis (RA), type I diabetes, systemic lupus erythematosus, and juvenile idiopathic arthritis." (PMID 30054208, 2018). "This study investigated the association between single nucleotide polymorphisms (SNPs) in TRAF1/C5 and PTPN22 genes and rheumatoid arthritis (RA) in a Han Chinese population." (PMID 21492465, 2011). "For example, variants in PTPN22 are associated with rheumatoid arthritis (RA), type-1-diabetes (T1D) and Crohn's disease (CD)." (PMID 21152001, 2010).
rheumatoid arthritis (continued). "The functional single-nucleotide polymorphism (SNP) of the gene PTPN22 is a susceptibility locus for rheumatoid arthritis (RA)." (PMID 16635271, 2006). "This study aimed to investigate the associations of PTPN22 and PADI4 gene polymorphisms with rheumatoid arthritis (RA) susceptibility and disease activity in the Aswan population." (PMID 40983977, 2025). "Current research on PTPN22 mainly focuses on rheumatoid arthritis, type 1 diabetes and autoimmune thyroid disease." (PMID 39238070, 2024). "For example, the protein tyrosine phosphatase non-receptor type 22 (PTPN22, rs2476601) have been found to be associated with type 1 diabetes, autoimmune thyroid disease, SLE, and rheumatoid arthritis." (PMID 38943194, 2024). "PTPN22 gene has been proved by researchers to play an important role in type I diabetes and rheumatoid arthritis (Carmona and Martín, 2018)." (PMID 35692826, 2022). "In genome-wide associations studies (GWAS), the single nucleotide polymorphism (SNP) rs2476601 within the PTPN22 locus was identified to increase the risk for autoimmune disorders such as type 1 diabetes (T1D), rheumatoid arthritis (RA), systemic lupus erythematosus and Graves’ disease." (PMID 32751912, 2020). "We also observed a significant hit in PTPN22 and the GWAS results correlated with the genetics of rheumatoid arthritis and psoriasis." (PMID 32888428, 2020). "A genetic correlation analysis of the penicillin allergy GWAS results in the current study revealed overlap with rheumatoid arthritis, even when excluding the PTPN22 region from the analysis." (PMID 32888428, 2020). "For example, PTPN22 had a very significant p value for rheumatoid arthritis, 2.34E−121, according to the tissue-selective expression ranking while it only had a p value 1 according to the statistical significance ranking." (PMID 31694669, 2019). "It is important to note that until now there are no studies that compare status or levels of anti-CCP antibodies with PTPN22 haplotypes in rheumatoid arthritis patients; in this respect, our study is the first of its type." (PMID 28210620, 2017). "Genes involved in regulating peripheral tolerance were found have effects on the development of RA, such as PTPN22 C1858T (rs2476601), CTLA-4 A49G, and PDCD-1 (rs36084323), and PD-L1 6777G was associated with the prevalence of rheumatoid nodules." (PMID 28969061, 2017). "A C-to-T single nucleotide polymorphism, which is located at position 1858 of PTPN22 cDNA and converts an arginine to a tryptophan, is associated with a higher risk of rheumatoid arthritis (RA), systemic lupus erythematosus (SLE), and type 1 diabetes but reduces the risk of Crohn’s disease." (PMID 24433447, 2014). "Previous studies in Mexican populations have described the allele and haplotype frequency distributions of the PTPN22 gene in SLE and susceptibility to rheumatoid arthritis." (PMID 25289035, 2014). "Our data depict a model that can reconcile the conflicting observations on the functional impact of the C1858T SNP and also suggest that PTPN22.6 is a novel biomarker of rheumatoid arthritis." (PMID 22427951, 2012). "More importantly, the level of PTPN22.6 in peripheral blood correlates with disease activity of rheumatoid arthritis." (PMID 22427951, 2012). "This study investigated five confirmed rheumatoid arthritis (RA) susceptibility genes/loci (HLA-DRB1, PTPN22, STAT4, OLIG3/TNFAIP3 and TRAF1/C5) for association with susceptibility and severity in an inception cohort." (PMID 20353580, 2010). "More speculative therapeutic targets such as PTPN22 in rheumatoid arthritis were also suggested to restore immune homeostasis." (PMID 39483464, 2024). "The gain-of-function variant of protein tyrosine phosphatase non-receptor type 22 (PTPN22) encodes the expression of a lymphoid-specific tyrosine phosphatase (master regulator of the immune response) and increases the risk of rheumatoid arthritis." (PMID 39483464, 2024).